CD46 (CD46 molecule)
Diseases named in the same sentence as CD46 in open-access papers (continued):
Sharing a sentence is not in itself a finding about the gene and the disease.
tumor (continued). "Studies have found that tumor cells can block complement activation cascades and inhibit MAC formation via membrane complement regulatory proteins (mCRPs), such as CD46, CD55, and CD59." (PMID 37907575, 2023). "CAR expression is often downregulated on malignant tumor cells and tumor cells undergoing EMT, whereas CD46 is ubiquitously expressed on almost all cells except for erythrocytes." (PMID 37856461, 2023). "In tumour samples, the intercellular interactions were mainly active in signalling pathways, including pathways involving SPP1, VTN, NOTCH, THY1, and CD46." (PMID 36860314, 2023). "In this respect, we observed increased expression levels of mCRPs, such as CD46, CD55, and CD59, in P3 tumor cells over the course of CTL-mediated immune editing." (PMID 35606403, 2022). "In a recent investigation, the anti-CD46 (fully human full-length IgG1) antibody YS5, labeled with the radioisotope zirconium-89, demonstrated superior tumor-to-background ratios than [68Ga]Ga-PSMA-11 in murine models." (PMID 36289795, 2022). "Overexpression of membrane bound complement regulators such as CD46, CD55, and CD 59 and blocking complement activation at the level of C3b also prevent CDC and efficient tumor cell killing." (PMID 35860237, 2022). "For example, MV and polio virus enter tumor cells by binding to CD46 and CD155, which are highly expressed on tumor cells." (PMID 36159398, 2022). "Taken together, our data indicate that mCRPs, such as CD46, CD55, or CD59, are increased during CTL-mediated immunoediting, and they, especially CD59, contribute to CDC resistance of immune-edited tumor cells." (PMID 35606403, 2022). "For example, siRNA-mediated downregulation of CD46, CD55 and/or CD59 on several primary tumors and tumor cell lines sensitizes them to CDC." (PMID 33147799, 2020). "Upregulation of tumor promoting genes in the PD-L1 positive group were notable for CD68, MED19 and CD46." (PMID 33415077, 2020). "PD-L1 expression positively correlated with high expression levels of tumor promoting genes such as CD68, ADAM12, FXYD5, S100A11, CD46, and MED19 (and ST1D)." (PMID 33415077, 2020). "From the evidence provided in this review, we believe that Ads other than HAdV-C5, that target for instance CD46 or DSG-2, would be most suitable for the targeting and killing of the majority of tumor types." (PMID 32957644, 2020). "The seven discordant sites occur in seven protein-coding genes, including CD46 (an immune type I receptor) and ING5 (a tumor suppressor)." (PMID 31850058, 2019). "This has shown to be due to the influence of membrane-bound complement regulatory proteins such as CD46, CD55, and CD59 which are overexpressed in tumour cells." (PMID 31544882, 2018). "To further investigate the in vivo efficacy of the CD46-targeted Ad5/35-tk/GCV, we used a xenograft tumor model in nude mice." (PMID 30201920, 2018). "In a human EJ bladder cancer xenograft mouse model, with either overexpressed or suppressed CD46 expression levels, Ad5/35-tk followed by ganciclovir (GCV) treatment significantly affected tumor growth, whereas Ad5-tk/GCV had only minimal effects." (PMID 30201920, 2018). "The CAR expression level of all the tumor cells was lower than that of HEK293 cells, whereas the CD46 level in the tumor cells was greater than that in HEK293 cells except MIA-PaCa-2 and MSTO-211H cells." (PMID 28874135, 2017). "Levels of factor X (FX) and neutralizing antibodies (nAbs) in ascitic fluid were quantified and tumor cells were assessed for the expression of coxsackie virus and adenovirus receptor (CAR) and CD46." (PMID 27229159, 2016).
tumor (continued). "Successful infection and viral propagation is dependent upon high expression of CD46 on the target cell membrane, and this reliance on receptor abundance allows MV-NIS to functionally discriminate between normal and tumor cells." (PMID 23134812, 2012). "NPA cells expressed all the three proteins, with a greater expression of CD59 and CD55 than CD46 proteins, suggesting that NPA tumour cells were obviously protected against CDC." (PMID 20145622, 2010). "In NT2-N neuronal cell lines, relatively high expression levels of CD46, CD59 and CD55 are found, however, NT2-N are differentiated from NTERA-2 tumour cells (malignant pluripotent embryonal carcinoma) and tumours are known to overexpress these CReg proteins." (PMID 19721814, 2009). "The lack of MAC was probably due to the expression of C membrane regulators CD46, CD55 and CD59 on the tumour cells." (PMID 15726105, 2005). "Noteworthy membrane-bound CRPs in tumors include CD46, CD55, and CD59, while soluble ones encompass factor I, factor H, and properdin.Although CD46, CD55, and CD59 are pivotal complement regulators expressed across most cell types and tumor cells, they exhibit a double-edged sword role." (PMID 40370471, 2025). "It is noted that live attenuated measles viruses are not tumor specific since the natural receptors for these viruses, i.e., CD46 and signaling lymphocyte-activation molecule (SLAM), are ubiquitously distributed." (PMID 37040283, 2023). "This phenomenon could be due to the expression of several different complement-regulatory proteins (CRPs) by tumor cells, such as CD46, CD55, and CD59, which inhibit complement activation and confer resistance of tumor cells to killing mediated by CDC." (PMID 35804808, 2022). "Further, we confirmed that anti-tumor immunity does not depend on tumor CD46 expression by stimulation of splenocytes with both parental and CD46-positive FC1245 cells." (PMID 36726983, 2022). "Recently, it was reported that MV has significant anti-tumor activity against GBM and glioma stem cells in vitro and in vivo, a sensitivity that is at least in part explained by the overexpression of the MV receptor CD46 in brain tumor cell lines." (PMID 36366531, 2022). "The expression of inhibitory mCRPs like CD46, CD55 and CD59 can protect tumor cells from CDC." (PMID 36119088, 2022). "The rest genes, CD46, CXCL6, GPI, ITGB1, PLA2G6 and TNFSF4, were revealed for the negative association with tumor suppression." (PMID 35832540, 2022). "Similarly to these soluble regulators, the membrane-bound C inhibitors CD46, CD55 and CD59 are up-regulated in various primary tumors and tumor lines to evade the C attack." (PMID 33643290, 2020). "The overexpression of CD46 occurs in many, although not all, other common tumor types but usually to a lesser magnitude." (PMID 33147799, 2020). "A positive correlation (not significant) was observed between CD46 RNA expression levels in the tumor tissue from the 12 patients and the number of CD8+ TILs (Spearman's rank correlation, R = .4085; P = .1874)." (PMID 31944306, 2020). "Similarly, the membrane-bound complement inhibitors (e.g. CD46, CD55, and CD59) are up-regulated in various primary tumors and tumor lines to evade the complement attack." (PMID 33193442, 2020). "Apart from CD59, CD46, and CD55 could also enable tumor cells to evade CDC and function as complement regulators." (PMID 31685825, 2019). "A Western blot analysis of biopsy material derived from the three different tumor types revealed that CD46 expression in the xenograft tumors was not altered, and also was not influenced by the treatment modality." (PMID 30201920, 2018). "While the expression of both CAR and CD46 was very low in normal urothelium (data not shown), tumor cells derived from the bladder epithelium showed mixed results." (PMID 30201920, 2018). "Lastly, we observed that all tumor samples from patients with CRC stained strongly with the group B adenovirus receptors CD46 and DSG2 (data not shown)." (PMID 28923104, 2017).
tumor (continued). "In such a situation, it may be worth considering to also extend the receptor usage of VSV-CD133 to CD46, since our data show that MV-CD46/CD133 was superior over MV-CD133 in both tumor models." (PMID 28695108, 2017). "However, NCH644 tumor spheres contain more than 90% CD133-positive cells and infection with VSV-MV, relying on CD46 for cell entry, showed the same recovery of the cells observed for VSV-CD133." (PMID 28695108, 2017). "CD46 (membrane cofactor protein, MCP) is expressed broadly on the surface of somatic cells in humans and plays a pivotal role in the cell’s self-protection against the complement, which is also used by tumour cells." (PMID 27666019, 2016). "Since the sensitivity of MPM tumor cell lines to MV replication did not correlate with the CD46 expression level, we sought to identify other factors that condition sensitivity to MV replication." (PMID 26539644, 2015). "Our data also show that the sensitivity of tumor cell lines is not correlated to overexpression of the MV cell receptor CD46, contrary to what has been described in the literature." (PMID 26539644, 2015). "The overexpression of CD46 is probably not the only factor that conditions the ability of MV to preferentially replicate in and kill tumor cells." (PMID 26539644, 2015). "Numerous studies have reported SLAM, CD46 and PVRL4 as being tumor cell markers." (PMID 24892636, 2014). "The intensity of CD46 expression has been negatively correlated with histological grade and type, tumour size, and tumour recurrence but not to overall survival, which is supported by the results from this study." (PMID 20553615, 2010). "The proteins ADIPOR1, ADORA1 and CD46 did not demonstrate differences in expression between tumours from alive and dead patients." (PMID 20553615, 2010). "Ofcourse, the tumor rejection antigens and stage specific antigens have been well characterized on human embryos, but there are many others such as the TEC antigens (TEC1- TEC4), LeX, LeY, CD46, CD55, and CD59." (PMID 16033656, 2005). "However, CD46 is present at basal levels in normal tissues as well, meaning it is not a tumor-restricted marker." (PMID 41294877, 2025). "Therefore, simultaneously targeting CD46 and TREM1 may yield synergistic effects, more effectively blocking tumor immune evasion mechanisms and enhancing the body’s antitumor immune response." (PMID 41415031, 2025). "However, because CD46, CD55, and CD59 are constitutively expressed in human tissues, nonspecific targeting of these molecules can lead to undesired complement activation outside the tumor." (PMID 35860237, 2022). "Overall, our results indicate that CD46 expression by tumor cells is necessary for the attachment of BVDV, but it is not sufficient to turn cells susceptible to infection and to achieve the oncolytic effect of BVDV, thus suggesting the involvement of other mechanisms." (PMID 32653014, 2020). "In addition, CD46 (membrane cofactor protein), could facilitate the inactivation of C3b by serum factor I, but the role of CD46 in protection tumor cells from the attack of complement system remains unknown." (PMID 31118022, 2019). "While CAR expression was not correlated with disease progression (data not shown), CD46 expression was negatively correlated with tumor stage (p = 0.017), tumor grade (p = 0.012), and European organisation for research and treatment of cancer (EORTC) risk group (p = 0.042)." (PMID 30201920, 2018). "Overall, this study suggests that about 70% of MPM patients are potentially sensitive to MV oncolytic activity and that this activity depends on defects in the intracellular innate antiviral response in MPM tumor cells rather than on CD46 overexpression on the cell surface." (PMID 26539644, 2015).
tumor (continued). "Notably, CD46 and TREM1 may collaboratively shape a tumor-promoting microenvironment: CD46 potentially mediates immunosuppression via T-cell regulation, while TREM1 drives sustained production of pro-inflammatory factors (e.g., TNF-α, IL-6) by amplifying NF-κB signaling." (PMID 41415031, 2025). "However, CD46 is not a tumor-selective receptor because of its expression on normal cells." (PMID 36311790, 2022). "The expression of human CD46 by the tumor is absolutely necessary for achieving a therapeutic effect by mLOAd703, which was also confirmed by the fact that no treatment effect was achieved in several other murine tumor models and a hamster tumor model, which all lack CD46 expression." (PMID 35141399, 2022). "However, complement deficiencies, the over-expression of membrane complement regulatory proteins (e.g. CD55, CD59, and CD46) and fluid phase inhibitors (e.g. CFH, CFHR5, and C4BP) in the tumor microenvironment often cause resistance and non-responsiveness to mAb treatment." (PMID 33193442, 2020). "Of note, Enadenotucirev, the virus that fails to infect CD46-negative murine ECs, downregulates VEGF in infected areas of human tumor xenografts, which coincides with the decreased vascular perfusion." (PMID 35284629, 2022). "Altogether these data show that a majority of tumor MPM cell lines overexpress CD46 as the only known MV receptor and that sensitivity of these cells to MV infection is not related to CD46 expression." (PMID 26539644, 2015). "However, we failed to observe a correlation between the level of CD46 expression and the sensitivity of MPM tumor cell lines to MV replication." (PMID 26539644, 2015). "Tumor targeting results obtained in mice with chimeric Ad5 viruses containing Ad3 or Ad35 fibers also point in this direction because the Ad3 fiber binds to human DSG2 but not to mouse DSG2, and in mice the Ad35 fiber receptor CD46 is expressed only in testis." (PMID 28548059, 2014). "A possible explanation for the absent correlation between viral replication and anti‐tumour activity could be that murine CAR can function as a receptor for hAds, unlike murine CD46, thereby increasing the relative amount of (non‐cancerous) cells that might support limited replication of HAdV‐C5." (PMID 38037840, 2024).
infection (140 papers, 2006 to 2026). The state of being infected such as from the introduction of a foreign agent such as serum, vaccine, antigenic substance or organism. "Infection of a CD46-deficient porcine cell line suggested that CD46, which is implicated in the viral entry of several pestiviruses, is not a major factor for the viral entry of PhoPeV." (PMID 39861896, 2025). "Serial passage of BVDV on CD46-edited MDBK cells selected for virus variants capable of CD46-independent infection." (PMID 40431646, 2025). "The loss of CD46 likely reduces the infection efficiency and transgene expression by mLOAd703 in vivo, especially at later treatment time points." (PMID 35141399, 2022). "Using a genetic approach, knockouts of CD9 in SupT1 cells had reduced expression of immediate early transcripts but deficiency for CD46 showed abolished binding and reduced infection in SupT1 cells." (PMID 33968023, 2021). "As the LOAd703 virus needs human CD46 for infection, encodes human transgenes and cannot replicate in mice, the combination therapy cannot be evaluated in immunocompetent syngeneic mice models." (PMID 33666760, 2021). "SK6 cells inducibly expressing the fluorophore labelled, cellular surface receptor, bovine CD46 were chosen as system to study the infection cycle, as these cells demonstrated a high susceptibility to infection with BVDV after induction." (PMID 31963539, 2020). "These cell lines were previously shown to express abundant levels of the measles virus receptor CD46 and were susceptible to infection with an attenuated Edmonston-strain MV." (PMID 23134812, 2012). "Changes in CD46 expression could influence viral entry, immune evasion, and disease progression, making it a potential diagnostic and immunological marker for infection monitoring." (PMID 41012793, 2025). "HOZOT cells showed remarkably high CD46 protein expression and slight expression of integrin proteins, but no CAR protein expression was detected, suggesting that HOZOT cells are susceptible to infection with adenovirus serotype 35 fiber–modified adenovirus (Ad/F35), which can bind to CD46 protein." (PMID 27901098, 2016). "Therefore, the differential regulation of CD46 surface expression could potentially underlie one explanation for the different MS susceptibility between these herpesviruses’ infections." (PMID 36032156, 2022). "Interestingly, a recent study based on the construction of a knock-out cell line showed that different BVDV isolates display markedly reduced infection of CD46 deficient cells, but viruses that escape CD46 dependency were rescued upon passaging in knock-out cells." (PMID 34204224, 2021). "For this maximal virus volume infection, the reduced infectivity of the PI-86-2022 isolate in CD46-edited lymphocytes achieved statistical significance (p < 0.002)." (PMID 40431646, 2025). "Through an initial screening, several monoclonal antibody clones were identified that bind to Ad11 particles and inhibit infection of Ad11 to HEK293 cells which endogenously express human CD46." (PMID 40561062, 2025). "Ad11 and some Ads from Group D use human CD46 as a primary receptor for infection, whereas Ad5 uses Coxsackievirus-Adenovirus Receptor (CAR)." (PMID 40561062, 2025). "CD46 dependence for infection correlated in most cases well with avidities, including low avidities between HAdV-D37 and D39 and CD46, but also with some exceptions, such as relatively high avidity between HAdV-D32 and CD46." (PMID 40980888, 2025). "Even when using the maximum volume of each virus for infection, the adapted viruses were highly restricted in their ability to infect lymphocytes from the CD46-edited heifer." (PMID 40431646, 2025). "Previous studies have shown that HAdV-D56 initiates infection via a direct interaction between the hexon protein and CD46, while HAdV-D26 utilize sialic acid located at the apex of the fiber knob as their adenovirus receptor." (PMID 40400688, 2025).